MTAP (methylthioadenosine phosphorylase)
Diseases named in the same sentence as MTAP in open-access papers (continued):
Sharing a sentence is not in itself a finding about the gene and the disease.
malignant pleural mesothelioma (9 papers, 2013 to 2023). A malignant neoplasm that arises from mesothelial cells in the pleura and shows a diffuse growth pattern. "Loss of expression of BRCA1 associated protein (BAP1) or methylthioadenosine phosphorylase (MTAP) or homozygous deletion of cyclin‐dependent kinase inhibitor 2A (CDKN2A) (p16) by FISH helps to distinguish reactive mesothelial cells from malignant pleural mesothelioma." (PMID 36069384, 2022). "Zimling, Jorgensen, and Santoni-Rugiu conducted a study where they analyzed MTAP reactivity in 99 cases of malignant pleural mesothelioma (MPM)." (PMID 36913304, 2023). "Zimling, Jorgensen and Santoni-Rugiu, studying MTAP immunoreactivity in 99 malignant pleural mesotheliomas (MPMs), found that 65% of the tumors analyzed had a decreased reactivity to MTAP." (PMID 26751376, 2016). "This antibody has previously been validated for detection of MTAP in malignant pleural mesothelioma, gastro-intestinal tumors and chordoma providing further evidence of its specificity." (PMID 24069379, 2013). "Previous work has used immunohistochemistry to reliably detect MTAP expression in formalin-fixed, paraffin-embedded malignant pleural mesothelioma." (PMID 24069379, 2013). "Homozygous, hemizygous and no loss of methylthioadenosine phosphorylase (MTAP) detected by droplet digital PCR (ddPCR) in malignant pleural mesothelioma (MPM) samples." (PMID 33304846, 2020). "Homozygous, hemizygous and no loss of methylthioadenosine phosphorylase (MTAP) detected by fluorescence in situ hybridization (FISH) in malignant pleural mesothelioma (MPM) cases." (PMID 33304846, 2020). "Comparison of fluorescence in situ hybridization (FISH) results for detecting methylthioadenosine phosphorylase (MTAP) and CDKN2A deletion in malignant pleural mesothelioma (MPM) cases." (PMID 33304846, 2020). "Comparison of droplet digital PCR (ddPCR) results for detecting methylthioadenosine phosphorylase (MTAP) and CDKN2A deletion in malignant pleural mesothelioma (MPM) cases." (PMID 33304846, 2020). "CDKN2A is frequently co-deleted with MTAP, while the status of MTAP IHC expression reflected the status of CDKN2A in malignant pleural mesothelioma diagnosis." (PMID 31965001, 2020). "We hypothesized that small molecule transcriptional perturbation could be harnessed to target a cellular dependency involving protein arginine methyltransferase 5 (PRMT5) in the context of methylthioadenosine phosphorylase (MTAP) deletion, seen frequently in malignant pleural mesothelioma (MPM)." (PMID 33795785, 2021).
prostate carcinoma (9 papers, 2013 to 2025). A carcinoma that arises from epithelial cells of the prostate gland. "A higher level of MTAP staining was linked to TMPRSS2:ERG fusion positive prostate cancers (p < 0.0001)." (PMID 40554389, 2025). "FISH validation not only confirmed the MTAP deficiency in all 9 selected cases but also demonstrated that the MTAP expression loss in prostate cancer is indeed caused by homozygous 9p21 deletions." (PMID 40554389, 2025). "The analysis of 13,189 prostate cancers identified only 33 cases (0.3 %) with a complete MTAP loss, indicating that MTAP deficiency is a rare event in prostate cancer." (PMID 40554389, 2025). "The absence of associations with tumor phenotype and PSA recurrence seen in this study argues against a major clinical impact of MTAP deficiency in prostate cancer." (PMID 40554389, 2025). "Taken together, the results of our study demonstrate that MTAP deficiency is exceedingly rare in prostate cancer, while high MTAP expression is a strong and independent marker for poor prognosis in ERG negative cancers." (PMID 40554389, 2025). "The castration-resistant prostate cancer cells used in this study, C4-2 and DU145, are MTAP-proficient, thus the differential toxicity of 6-TG in cancer versus normal prostate cells cannot be ascribed to a deficiency of MTAP in prostate cancer cells." (PMID 31284411, 2019). "However, MTAP is very rarely mutated in prostate cancer as it plays an essential role in the homeostatic regulation of prostate cells’ metabolite pools." (PMID 31284411, 2019). "Furthermore, we find that genetic and pharmacological based loss of MTAP function reduces prostate cancer cell line growth in vitro, and as xenografts." (PMID 26910893, 2016). "However, examination of a variety of publically available datasets, cell lines, and tissue specimens indicates that loss of MTAP is rare in prostate cancer." (PMID 26910893, 2016). "Our findings - including the significant association with AR expression - are also in agreement with functional evidence for androgenic regulation of MTAP expression and a role of MTAP for prostate cancer cell growth." (PMID 40554389, 2025). "A query of the cBioportal database (05.06.2024) including 2,565 prostate cancers with copy number profiling from 24 studies revealed 33 (1.24 %) tumors with “deep” (largely corresponding to a homozygous deletion) MTAP deletion." (PMID 40554389, 2025). "All these findings are in line with a significant functional role of MTAP in prostate cancer cells which deserves further investigation." (PMID 40554389, 2025). "The mechanism by which ERG expression reversed the role of MTAP in prostate cancer cells is unclear and cannot be determined from our data." (PMID 40554389, 2025). "In a follow-up study, the same group further reported increased apoptosis after ex vivo treatment of human prostate cancers by a combinatorial treatment including the MTAP inhibitor Methylthio-DADMe-Immucillin-A (MTDIA)." (PMID 40554389, 2025). "Prostate cancer cells depend on MTAP, the rate-limiting enzyme involved in the methionine salvage pathway, to cope with increased polyamine biosynthesis." (PMID 31911608, 2020). "Here, the authors show that inducing upregulation of polyamine biosynthesis and targeting MTAP synergize to increase apoptosis in prostate cancer cells." (PMID 31911608, 2020). "Prostate cancer (CaP) relies on methylthioadenosine phosphorylase (MTAP), the rate-limiting enzyme, to relieve strain." (PMID 31911608, 2020). "A recent study with prostate cancer cells silenced for MTAP also showed similar growth rates to controls." (PMID 32093414, 2020). "We report near universal retention of MTAP expression in a panel of human prostate cancer cell lines as well as patient samples." (PMID 26910893, 2016). "Upon metabolic perturbation, prostate cancer cell lines upregulate MTAP and this correlates with recovery of SAM levels." (PMID 26910893, 2016).
prostate carcinoma (continued). "If MTAP is required for prostate cancer to maintain growth, it would be expected that CaP would retain the MTAP locus despite its close proximity to the commonly deleted p16 locus." (PMID 26910893, 2016). "For example, knockdown or inhibition of MTAP (S-methyl-5′-thioadenosine phosphorylase) by shRNA or treatment with Methylthio-DADMe-Immucillin-A (MTDIA) blocks androgen sensitive prostate cancer growth in vivo, suggesting this methionine salvage pathway is important for PCa cell survival." (PMID 34068137, 2021). "Finally, we show that knockdown of MTAP, both genetically and pharmacologically, blocks androgen sensitive prostate cancer growth in vivo." (PMID 26910893, 2016). "Therefore, this pathway, and specifically the MTAP enzyme, is an attractive therapeutic target for prostate cancer." (PMID 26910893, 2016). "We hypothesized that given its apparent critical role in homeostatic control of SAM pools in prostate, MTAP is necessarily conserved in most prostate cancers, making it a potential therapeutic target." (PMID 26910893, 2016). "Indeed this dependency may highlight a unique therapeutic approach to targeting prostate cancer through inhibitors of Methylthioadenosine Phosphorylase (MTAP), the rate limiting enzyme." (PMID 28216563, 2017). "Interestingly, we found that the TRAMP C2G prostate cancer cell line exhibited a drop in SAM pools upon folate deficiency, but that by 20 PDs the SAM pools recovered and this correlated with increased expression of MTAP while SAM pools were low." (PMID 26910893, 2016). "In summary, we report that the BRD4-PRMT5/MTAP axis regulates FUBP1 methylation and is essential for prostate cancer progression." (PMID 39146021, 2024). "The rate-limiting enzyme involved in this process is methylthioadenosine phosphorylase (MTAP), which, although commonly deleted in many cancers, is protected in prostate cancer." (PMID 26910893, 2016).
squamous cell carcinoma (9 papers, 2014 to 2025). A carcinoma arising from squamous epithelial cells. "Loss of mTAP expression was observed in five (of 34, 14.7%) thymic carcinomas, including three squamous cell carcinomas, one sarcomatoid carcinoma, and one adenosquamous carcinoma." (PMID 35565429, 2022). "In cases in which we had results of CDKN2A FISH studies and mTAP IHC, we identified a concordant homozygous deletion of CDKN2A and loss of expression of mTAP in two squamous cell carcinomas." (PMID 35565429, 2022). "Interestingly, histology distribution was also different among cases and controls (p<0.001): while adenocarcinoma was similarly represented as the prevalent histology, squamous cell carcinoma cases were fourfold more common in the MTAP loss cohort." (PMID 38350716, 2025). "The investigation provided insight into the distribution of MTAP deletion across diverse histological subtypes, revealing 50% adenocarcinomas, 42% squamous cell carcinomas, and 8% large cell carcinomas, from the set of samples analyzed." (PMID 38001653, 2023). "In four carcinomas with homozygous deletion of CDKN2A, mTAP expression was lost in two squamous cell carcinomas and in a subset of tumor cells of an adenocarcinoma and was preserved in a lymphoepithelial carcinoma." (PMID 35565429, 2022). "Notably, adenocarcinomas exhibited a heightened incidence of MTAP deletion at 44%, compared to a 29% deletion rate in squamous cell carcinomas." (PMID 38001653, 2023). "13.4% (3928/29,379) NSCLC cases exhibited MTAP loss distributed in adenocarcinoma (59%), squamous cell carcinoma (22%), NSCLC not otherwise specified (16%), and 1% each for large‐cell neuroendocrine, sarcomatoid, and adenosquamous carcinoma." (PMID 35747993, 2023). "Interestingly, in one of our thymic squamous cell carcinomas, NGS revealed CDKN2A/B loss despite normal CDKN2A FISH results and expressed mTAP." (PMID 35565429, 2022). "Therefore, we evaluated mTAP expression in TET and found a loss of cytoplasmic expression in 15% of thymic carcinomas, most of which (60%) were squamous cell carcinomas." (PMID 35565429, 2022). "In two cases of thymic carcinoma (both squamous cell carcinomas) with homozygous deletion of CDKN2A, mTAP expression was lost; in a lymphoepithelial carcinoma with homozygous deletion of CDKN2A, mTAP was expressed." (PMID 35565429, 2022). "Using BAP1, mTAP, CD117 (cut-off, 10%), and TdT, 88.9% of thymic carcinomas (95.7% of squamous cell carcinomas) and 77.8% of thymomas could be predicted." (PMID 35565429, 2022).
chordoma (8 papers, 2010 to 2025). Chordomas are rare malignant tumors arising from embryonic remnants of the notochord in axial skeleton. "The genetic alteration (deep deletion) frequency showed that 1/3rd of the chordoma samples have MTAP loss and CDKN2A, CDKN2B and CDKN2C loss; however, there is no loss in the folate pathway genes in the samples analyzed in personalized oncogenomics cBioPortal." (PMID 37147496, 2023). "Previously published studies have shown that MTAP loss has implications on chordoma." (PMID 36572880, 2022). "Furthermore, MTAP loss is also significant in rare tumors such as chordoma." (PMID 36572880, 2022). "The CDKN2A/MTAP locus is frequently deleted in chordoma, suggesting an opportunity for repurposing PRMT5 or MAT2A inhibitors." (PMID 36387127, 2022). "Several clinical trials are on-going which use Pemetrexed for different types of cancers like chordoma (NCT03955042), and MTAP deficient urothelial cancer (NCT03744793, NCT05335941)." (PMID 36572880, 2022). "These cell lines also harbor genetic changes, such as loss of p16, MTAP, or PTEN, that make them potentially useful models for studying mechanisms of chordoma pathogenesis and for evaluating targeted therapies." (PMID 21253487, 2010). "Significant enrichments were identified in dedifferentiated chordoma, specifically for CARM1 (100%, p < 10−10), PRKN (66.67%, p < 10−10), and MTAP (100%, p = 0.009), suggesting these mutations may uniquely characterize dedifferentiated chordoma." (PMID 39941902, 2025). "It is, therefore, tempting to speculate that TBXT-mediated MTAP suppression may phenocopy this effect in chordoma." (PMID 40901948, 2025). "As MTAP and TYMS are involved in important cellular processes, inhibition or loss of these genes have a major impact on the cellular processes and can possibly be explored further for use as therapeutic targets in chordoma." (PMID 37147496, 2023). "Recently, molecular features that could indicate the application of targeted therapies have been identified in chordoma, including activation of the PI3K/Akt/mTOR pathway, activation of the IGF1R signaling cascade, loss of methylthioadenosine phosphorylase, and activation of STAT3." (PMID 21253487, 2010).
gastric cancer (8 papers, 2013 to 2026). A primary or metastatic malignant neoplasm involving the stomach. "In gastric carcinomas, MTAP loss was associated with worse survival (p = 0.024), particularly in those who underwent primary surgery (p = 0.008)." (PMID 42129334, 2026). "Immunohistochemical MTAP loss consistently co-occurred with homozygous CDKN2A deletion and was present in 25.5% of cholangiocarcinomas, 9.3% of esophageal adenocarcinomas, 10.3% of gastric carcinomas, and 30.2% of pancreatic adenocarcinomas." (PMID 42129334, 2026). "MTAP-ANRIL fusion has been reported in melanoma and CLDN18-ARHGAP26 in gastric cancer, the latter promoting loss of the epithelial phenotype in gastric cancer.TMPRSS2 fusions may be defining markers for prostate cancer." (PMID 31007851, 2019).
malignant mesothelioma (8 papers, 2018 to 2025). A malignant neoplasm of the pleura or peritoneum, arising from mesothelial cells. "Loss of BAP1 and MTAP expression was instrumental in distinguishing malignant mesothelioma from benign mesothelial proliferations in this patient." (PMID 40662041, 2025). "After confirmation of the mesothelial lineage, BAP1 loss, CDKN2A homozygous deletion, and MTAP loss were the most specific markers for the diagnosis of malignant mesothelioma." (PMID 35205689, 2022). "A high correlation of MTAP immunohistochemical reactivity with CDKN2A homozygous deletion (as determined by FISH) was first reported in malignant mesothelioma with a sensitivity of 78% and specificity of 98%." (PMID 39117984, 2024). "For its proximity to CDKN2A, the methylthioadenosine phosphorylase (MTAP) gene is frequently co-deleted in different cancer types, including malignant mesothelioma." (PMID 34830817, 2021). "Therefore, CDKNA 9p21 evaluated by FISH and MTAP evaluated by immunohistochemistry are also useful for the diagnosis of malignant mesothelioma." (PMID 39006698, 2024). "In addition to the immune checkpoint LAG3, BAP1, NF2, and MTAP were chosen as proxies to represent commonly altered TSG products in malignant mesothelioma." (PMID 38994676, 2024). "The primary objective of this study was to advance our understanding of the malignant mesothelioma TIME while examining the protein expression levels for LAG3, BAP1, NF2, and methylthioadenosine phosphorylase (MTAP)." (PMID 38994676, 2024). "MTAP served as a surrogate marker for CDKN2A/B, as the MTAP gene, located at 9p21, is frequently codeleted with CDKN2A/B within distinct types of malignant mesothelioma." (PMID 38994676, 2024). "A prior study using a monoclonal anti-MTAP primary antibody reported acceptable specificity and sensitivity for MTAP immunohistochemistry in detecting the CDKN2A homozygous deletion and diagnosis of malignant mesothelioma." (PMID 38994676, 2024). "Overall, we could conclude that MTAP hypermethylation might not behave as a good biomarker for malignant mesothelioma." (PMID 30123503, 2018).